NME1 (NME/NM23 nucleoside diphosphate kinase 1)
Diseases named in the same sentence as NME1 in open-access papers (continued):
Sharing a sentence is not in itself a finding about the gene and the disease.
tumor (continued). "Our results were consistent with those of the meta-analysis such that GSN, SPTBN1, SFRP1 and MAF were down-regulated in most tumor samples with respect to their matched non-tumor samples whereas COX6C, RAD21, GSPT1, NME1 and PTTG1 were up-regulated." (PMID 19116033, 2008). "Compelling evidence shows that S10A4 is directly involved in the formation of metastases without affecting the initiation and growth of the primary tumor, hence appearing as a pro-metastatic protein, unlike NDPK-A/NME1 and NDPK-D/NME4 that are metastasis suppressors." (PMID 34674701, 2021). "Together, these findings led to the designation of NME1 as a metastasis suppressor gene (MSG), a term subsequently extended to all genes sharing the unique ability to suppress metastatic potential of cancer cells without impacting primary tumor growth." (PMID 28788083, 2017).
cancer (135 papers, 1995 to 2026). A tumor composed of atypical neoplastic, often pleomorphic cells that invade other tissues. "NME1 mRNA levels were strongly negatively associated with mRNA levels of ADAM10 in fifteen human cancer types." (PMID 33918324, 2021). "Mechanisms underlying the metastasis suppression of NME1 have been addressed in multiple types of cancer cells." (PMID 32977620, 2020). "For example, our deep analysis on the most well-known MS genes revealed that NME1 only have 5 mutations from 3 cancer types." (PMID 26486520, 2015). "Interestingly, NME1 was already associated with the invasion and metastasis of various cancer types but also induced neurite growth and neuroprotection in different model systems for Parkinson’s disease (PD) in vivo and in vitro." (PMID 37509196, 2023). "Additionally, NME1 mRNA levels are strongly negatively associated with mRNA levels of ADAM10 in many human cancers in the TCGA database." (PMID 33918324, 2021). "Moving forward, a more expansive inquiry into the conserved characteristics of NME1 + epi across a spectrum of cancer types would be an invaluable step." (PMID 39075485, 2024). "Whereas the role of NME1 in cancer has been extensively studied, the role of NME2 is less well understood." (PMID 39063217, 2024). "For malignant cells, consistently upregulated metabolic genes were predominantly associated with cancer hallmark pathways, including glycolysis (GAPDH, GPI and LDHA), OXPHOS (COX6B1 and ATP5MC2), and nucleotide metabolism (TK1, GUK1, NME1)." (PMID 39393173, 2024). "In our previous studies, we chose sponge and human cancer-related homologs with an already determined localization in human cancer cells, namely NME1) and NME6." (PMID 36827160, 2023). "Perturbations in cancer-related pathways, such as motility and cell adhesion, were also detected in fibroblasts as a result of either NME1- or NME2-containing EVs." (PMID 36010906, 2022). "It was worth noting that NME1 served as a metastasis suppressor in cancer cells, this enzyme decreased pEGFR and pAkt expression in a dynamin dependent manner and contributed to metastasis suppression via altering tumor endocytic and motility phenotypes." (PMID 35280744, 2022). "We suggest that EV-derived NME1 and NME2 cause decreased lipid production in fibroblasts, thereby inhibiting lipid supply of cancer cells provided by fibroblasts at this early stage of metabolic symbiosis." (PMID 36010906, 2022). "NME1 has multiple roles in cancer metastasis involving epithelial-mesenchymal transition, matrix proteolysis, and proinvasive signaling." (PMID 35259022, 2022). "On the other hand, reexpression of NME1 in invasive cancer cells has been thought to be a promising strategy for antimetastatic therapy; our results indicate that the suppression of NME1 by LCFA-CoA needs to be considered in future clinical practice." (PMID 35259022, 2022). "In cells, LCFA-CoA inhibited clathrin-mediated endocytosis and cancer cell migration, processes regulated by NME1/2." (PMID 35259022, 2022). "Here, by using gene silencing, inactivation and overexpression strategies in a variety of cellular models of cancer, we show that NME1 is a powerful inhibitor of EMT." (PMID 33918324, 2021). "In the present study, we show that the metastasis suppressor NME1 (also called NM23-H1) is a strong inhibitor of EMT in a large variety of cancer cell lines." (PMID 33918324, 2021). "Conversely, overexpression of NME1 in mesenchymal cancer cells resulted in a more epithelial phenotype." (PMID 33918324, 2021). "Transfection of the NME1 gene into different types of cancer cells has resulted in the inhibition of metastatic properties, including migration, invasion, and colonization." (PMID 32977620, 2020). "Further investigations are needed to clarify the controversy between NME1 expression in other cancer types to address the relationship between expression and clinicopathological features." (PMID 32197468, 2020).
cancer (continued). "NME1 expression suppresses the motile and invasive activities of cancer cells, and attention has largely focused on its interactions with signaling cascades in the cytoplasmic and cell membrane compartments." (PMID 32824412, 2020). "We further found that NME1 was involved in the cell cycle pathway, and the defect of cell cycle regulation has been reported to contribute to uncontrolled cancer cell proliferation." (PMID 32795291, 2020). "NME1 is a metastasis suppressor gene (MSG) that has provided valuable insights into mechanisms regulating cancer progression." (PMID 32824412, 2020). "Intriguingly, alteration of both intracellular and extracellular NME1/2 levels were shown to have implication in cancer progression." (PMID 31427986, 2019). "Acting on the mevalonate pathway to reduce secondary metabolites and ultimately counteract the activities of FDPS and NME1 looks attracting as a novel cancer therapy, in agreement with several data." (PMID 28962550, 2017). "Except two articles, all of the other reported their cut-off of NME1 expression, most of which identified more than about 50% staining cancer cells as high expression." (PMID 27518571, 2016). "Genetic polymorphisms in the nonmetastatic cell 1 gene (NME1) are reportedly associated with the risk of various tumors and the prognoses of cancer patients." (PMID 40417235, 2025). "However, this activity is complex; while NME1 is anti-metastatic in cancers of epithelial origin, it can also promote the initiation in other cancers." (PMID 39483891, 2024). "The mystery surrounding whether NME1 + epi represents a conserved subcluster common across various cancers further exacerbates this concern." (PMID 39075485, 2024). "In different cancer cell types, NME1 could bind to gelsolin, thereby inhibiting the actin depolymerizing function of gelsolin and decreasing cell migration." (PMID 39063217, 2024). "Some studies have demonstrated that NME1 promotes migration and invasion in cancer." (PMID 39063217, 2024). "Based on our evidence above that NME1 is a repressor of EMT, we predicted that its expression might be negatively associated with expression of EMT markers in human cancer." (PMID 33918324, 2021). "The metastasis-suppressor role of NME1 together with its promoting function of dynamin activity in endocytosis, as well as the regulation of MT1-MMP surface exposure through endocytosis raise the intriguing possibility of a control of MT1-MMP activity by NME1 NDPK in cancer cells." (PMID 34012098, 2021). "In addition, NME1 knockout correlated with a strong membranous MT1-MMP expression in carcinoma cells that increased in IBC vs. DCIS tumors." (PMID 34012098, 2021). "NME1 is known to inhibit the migratory and invasive potential of cancer cells." (PMID 33019537, 2020). "In addition to the nuclear translocation of β-catenin by NME1 silencing, Wnt/β-catenin-mediated resistance to cisplatin has been demonstrated in human cancers." (PMID 32977620, 2020). "However, it is known that there is a complex interplay between NME1 and β-catenin in a variety of cancers." (PMID 32977620, 2020). "NME1 depletion resulted in significantly more rapid migration of cells into scratch wounds, with significantly reduced wound width observed at approximately 24 h, consistent with the observed role of NME1 in adult cancer metastases." (PMID 32392889, 2020). "These concordant observations obtained in two cell lines of distinct cancer origins indicate induction of DSBs stimulates profound translocation of NME1 into the nucleus and recruitment of NME1 to focal structures within the nucleus that are associated with DSBR." (PMID 32824412, 2020).
cancer (continued). "Furthermore, NME1/2 expression levels are inversely correlated with patient’s prognosis in different cancer cohorts." (PMID 33019537, 2020). "Limited mutational analyses suggested that histidine kinase activity of NME1 may correlate with suppression of cancer cell motility." (PMID 32392889, 2020). "Regarding NME1, its relevance in cancer is still controversial." (PMID 32183400, 2020). "NME1 is initially identified for its metastatic suppressive potential for cancer cells." (PMID 29631596, 2018). "For instance, NME1 has been confirmed its metastasis suppressor role in 28 cancer types." (PMID 26486520, 2015). "Interestingly,KIAA0101, CANX and NME1 haveall been found to be highly expressed in at least eight different carcinomas,including breast, lung and prostate, representing possible globaltumor markers." (PMID 21423607, 2011). "Thus, we suggested that NME1 plays a different role in LUAD than many other cancers, and it may serve as a potential biomarker for LUAD." (PMID 32795291, 2020). "Disrupting the interaction between NME1/2 and PRUNE1, as suggested, holds the potential to be an excellent therapeutic target for the treatment of cancer and the inhibition of metastasis dissemination." (PMID 38180572, 2024). "When NME1 is depleted, p110 and AKT are activated, promoting migration and invasion of the cancer cells." (PMID 39063217, 2024). "In this study, we focused on the first identified metastasis suppressor NME1, and on its close homolog NME2, and investigated their function in EVs in the interplay between cancer and stromal cells." (PMID 36010906, 2022). "NME1 and SHMT2 genes are more expressed in cancer tissues and in metastatic samples when compared to normal tissues in several datasets." (PMID 33917317, 2021). "Among the genes, SPAG9, NME1, and NME2 are involved in regulating the proliferation of cancer cells." (PMID 30901931, 2019). "EBV-derived nuclear antigen 1 and nuclear protein EBNA-3C both interact with NME1 and reverse the metastasis-suppressive activity of NME1, indicating that these EBV proteins target and antagonize the functions of NME1 to promote cancer metastasis." (PMID 30158514, 2018). "Among the members of this gene family, NME1 and NME2 have been extensively studied for their cancer-suppressing activities." (PMID 25700270, 2015). "Most of the published studies have focused on the role of NME1 and NME2 in cancer independently of their histidine kinase function, which might help explain some of the contradictory results observed thus far." (PMID 39063217, 2024). "Thus, inhibition of NME1 by LCFA-CoA provides a molecular mechanism linking fatty acid metabolism and cancer metastasis, demonstrating the power of the chemical proteomic approach for discovering regulatory roles of metabolites." (PMID 35259022, 2022). "The interaction between NME1 and LCFA-CoA may represent a way for cancer cells to sense the dynamic changes of intracellular LCFA-CoA abundance, which helps the cancer cells to coordinate proliferation and invasion." (PMID 35259022, 2022). "A snaR-A-derived noncanonical miRNA, which targets NME-1, was recently identified and shown to promote cancer cell migration, suggesting a potential link between SNAR-A expression, cancer proliferation, and metastasis." (PMID 35637192, 2022). "In this context, the NM23-H1 (NME1) gene was shown to be a negative “Master Regulator” of cancer cells motility." (PMID 33931587, 2021).
cancer (continued). "Our data, when considered together with these previous findings, offer new insights to explain why cancer cells without NME1 are highly metastatic." (PMID 33918324, 2021). "Moreover, there is an inverse correlation between expression of NME1 and expression of markers of EMT in human cancer samples." (PMID 33918324, 2021). "Since depletion of NME1 from epithelial cancer cells induces an EMT phenotype, we wondered whether, conversely, overexpression of NME1 in mesenchymal cancer cells might restore an epithelial phenotype." (PMID 33918324, 2021). "NME1 (Nm23‐H1), a cellular target of the Epstein–Barr virus nuclear antigen EBNA3C, interacts with necdin and antagonizes necdin‐mediated growth suppression and anti‐angiogenic function in cancer cells." (PMID 34338396, 2021). "Some of these treatments could oppose the deregulations occurring in cancer samples, including those of the CHECK2, CYP51A1, HMGCS1, ITGA2, NME1 or VEGFA genes." (PMID 28962550, 2017). "For example, known disease genes BRCA2, CDH1, IDH1, CDKN2A, NME1 and FGFR3 frequently occurred at the top one in seven cancer types (including BC, GC, GBM, MB, MM, NB and OC), even though only two or three known-disease genes existed in NB, GBM and MB gene lists." (PMID 28076842, 2017). "In other cancers, regulating the Ras-MAPK pathway is another key molecular function of NME1." (PMID 27518571, 2016). "Our study does not exclude the possibility that NME1 may have a net genome-stabilizing effect through interactions with HR, NHEJ and A-NHEJ pathways in other cancers or in non-cancer settings." (PMID 32824412, 2020). "The gene name NME1 [NM23/NDP kinase (non-metastatic clone 23)] originated with the observed inverse correlation of its increased expression with decreased metastatic potential in mouse models and some human cancers." (PMID 33224873, 2020). "We confirm that metabolic pathways related to nucleotide biosynthesis, such as the NME1 signature, are related to highly proliferative tumors and have a role in HCC progression, although this role could be non-HCC-specific but common to other cancer types." (PMID 38927057, 2024).
infection (9 papers, 2009 to 2024). The state of being infected such as from the introduction of a foreign agent such as serum, vaccine, antigenic substance or organism. "We characterized the ubiquitination of the most enriched TRIM25 interactors, G3BP and UPF1, as well as two TRIM25-R54P specific interactors during infection, NME1, and PABPC4." (PMID 36067236, 2022). "Genes involved in pyrimidine metabolism (RRM2, CTPS1, TK1, NME1, NME2, and UCK2) were induced after infection with swH1N1 compared to huH1N1." (PMID 39247193, 2024). "In contrast, the eomesodermin (EOMES) gene is overexpressed, and nucleoside diphosphate kinase A (NME1), polycystic kidney disease 1-like 3 (PKD1L3), as well as nanos homolog 1 (NANOS1) are down-regulated in the infection group." (PMID 38474155, 2024). "Furthermore, other genes related to the pyrimidine pathway, namely NME1, NME2, and UCK2, were significantly higher expressed after infection with the swH1N1 relative to the pigs infected with huH1N1, albeit occasionally with modest fold changes." (PMID 39247193, 2024). "However, in FMDV-infected cells, NME1 protein levels decreased after 8 hpi, which became more marked as the infection progressed (8–16 h) and no cleaved bands were observed." (PMID 30158514, 2018).
digestive system neoplasm (2 papers, 2016 to 2020). A neoplasm (disease) that involves the digestive system. "The pooled odd ratios (ORs) and corresponding 95%CI were calculated to evaluate the prognostic value of NME1 expression in patients with digestive system neoplasms, and the association between NME1 expression and clinicopathological factors." (PMID 27518571, 2016). "Thus, we carried out a meta-analysis to evaluate the relationship between NME1 expression and the prognosis of patients with digestive system neoplasms." (PMID 27518571, 2016). "In digestive system tumors, NME1 also plays an critical role in many respects." (PMID 27518571, 2016).
neurological disorders (2 papers, 2022 to 2023). "Neurological disorders, including IVH, are associated with higher serum concentrations of NME1 and the decreased placental expression of CLN4." (PMID 36430274, 2022). "Moreover, higher serum NME1 concentrations were observed in relation to fetal distress, newborn neurological disorders, and IVH in the FGR group." (PMID 36768287, 2023). "Both serum NME1 levels and placental CLN4 expression in FGR pregnancies were significantly related to the incidence of neurological disorders in newborns." (PMID 36430274, 2022). "The serum NME1 concentrations are higher in the FGR group with brain-sparing effect and are increased in relation to fetal distress and neurological disorders, which may be useful in the prediction of IVH among FGR newborns." (PMID 36768287, 2023).
digestive system cancer (1 paper, 2016). A primary or metastatic malignant neoplasm involving any part of the digestive system. "The relationship between enhanced expression of NME1 and negative N status is false in all types of digestive system cancers." (PMID 27518571, 2016). "Among the clinical pathological factors evaluated, we could find that elevated NME1 expression was related to well differentiation and N status, but not to TNM stage, in patients with digestive system cancers." (PMID 27518571, 2016).
NME1 also shares sentences with these, for which no sentence is quoted: cervical carcinoma (10 papers); Stroke (9); lymphoma (7); nasopharyngeal carcinoma (7); acute myelogenous leukemia (5); leukemia (5); non-Hodgkin lymphoma (5); non-small cell lung carcinoma (5); hematologic malignancies (4); metastasis (4); acute lymphoblastic leukemia (3); adenocarcinoma (3); ductal carcinoma (3); endometrial cancer (3); head and neck squamous cell carcinoma (3); adenoma (2); B-cell lymphoma (2); bladder cancer (2); Cirrhosis (2); differentiated thyroid carcinoma (2); esophageal squamous cell carcinoma (2); heart failure (2); invasive carcinoma (2); ischemic stroke (2); myelodysplastic syndrome (2); neurodegenerative disease (2); pediatric cancer (2); peripheral T-cell lymphoma (2); prostate tumor (2); anaplastic carcinomas (1).
A further 46 diseases each share a sentence with NME1 in 1 paper.